SLC39A9 (solute carrier family 39 member 9)
Description:
Transports zinc ions across cell and organelle membranes into the cytoplasm and regulates intracellular zinc homeostasis. Participates in the zinc ions efflux out of the secretory compartments. Regulates intracellular zinc level, resulting in the enhancement of AKT1 and MAPK3/MAPK1 (Erk1/2) phosphorylation in response to the BCR activation. Also functions as a membrane androgen receptor that mediates, through a G protein, the non-classical androgen signaling pathway, characterized by the activation of MAPK3/MAPK1 (Erk1/2) and transcription factors CREB1 or ATF1 (By similarity). This pathway contributes to CLDN1 and CLDN5 expression and tight junction formation between adjacent Sertoli cells (By similarity). Mediates androgen-induced vascular endothelial cell proliferation through activation of an inhibitory G protein leading to the AKT1 and MAPK3/MAPK1 (Erk1/2) activation which in turn modulate inhibition (phosphorylation) of GSK3B and CCND1 transcription. Moreover, has dual functions as a membrane-bound androgen receptor and as an androgen-dependent zinc transporter both of which are mediated through an inhibitory G protein (Gi) that mediates both MAP kinase and zinc signaling leading to the androgen-dependent apoptotic process.
Synonyms: ZIP-9; ZIP9; FLJ11274
Tractability: Antibody: UniProt places it where antibodies can reach, with high confidence; its Gene Ontology location is reachable by antibodies, with high confidence; UniProt predicts a signal peptide or a membrane-spanning region. PROTAC: ubiquitination databases record sites on it; its protein half-life has been measured.
Gene: Protein-coding gene on chromosome 14 (69,398,015 to 69,462,390, forward strand). Ensembl gene ENSG00000029364.
Subcellular location: Golgi apparatus, trans-Golgi network membrane; Cell membrane; Cytoplasm, perinuclear region; Mitochondrion; Nucleus
Subcellular location (Human Protein Atlas): Endoplasmic reticulum
Gene Ontology:
Molecular function: androgen binding; G protein-coupled receptor activity; protein binding; zinc efflux transmembrane transporter activity; zinc ion transmembrane transporter activity; metal ion transmembrane transporter activity
Biological process: intracellular zinc ion homeostasis; regulation of vascular endothelial cell proliferation; zinc ion transmembrane transport; bicellular tight junction assembly; regulation of cellular response to testosterone stimulus; G protein-coupled receptor signaling pathway; metal ion transport; transmembrane transport; zinc ion transport
Cellular component: mitochondrial membrane; mitochondrion; nucleus; perinuclear region of cytoplasm; plasma membrane; trans-Golgi network; Golgi apparatus; membrane
Genetic constraint (gnomAD): Loss-of-function variants: 12 observed, 26.22 expected, observed/expected ratio (o/e) 0.46, 90% interval 0.29 to 0.74. The synonymous counts are far from expectation, so gnomAD's model fits this gene poorly and the ratio says little. Missense variants: 273 observed, 391.18 expected, observed/expected ratio (o/e) 0.7, 90% interval 0.63 to 0.77. Synonymous variants: 118 observed, 154.76 expected, observed/expected ratio (o/e) 0.76, 90% interval 0.66 to 0.89.
Homologues: Orthologues: chimpanzee SLC39A9 (100% identical), macaque SLC39A9 (99% identical), guinea pig SLC39A9 (95% identical), rabbit SLC39A9 (95% identical), rat Slc39a9 (95% identical), mouse Slc39a9 (93% identical), pig SLC39A9 (87% identical), dog SLC39A9 (86% identical), tropical clawed frog slc39a9 (85% identical), zebrafish slc39a9 (81% identical), Drosophila melanogaster Zip102B (51% identical), Caenorhabditis elegans zipt-9 (50% identical).
Diseases named in the same sentence as SLC39A9 in open-access papers:
SLC39A9 is named in the same sentence as 27 diseases in open-access papers, as found by Europe PMC text mining. Sharing a sentence is not in itself a finding about the gene and the disease. The quoted sentences say what the papers report.
bladder cancer (6 papers, 2020 to 2025). "For example, a pan-cancer TCGA analysis found that tumor overexpression of SLC39A3, SLC39A5, and SLC39A11 was associated with better overall survival after bladder cancer diagnosis, whereas tumor overexpression of SLC39A2, SLC39A8, SLC39A9, and SLC39A14 was associated with poorer survival." (PMID 39789109, 2025). "The analysis of TCGA database then revealed that the expression of SLC39A9 was considerably elevated in bladder cancers (vs. non-tumors), which was further associated with significantly worse disease-free survival (p = 0.003) or overall survival (p = 0.008)." (PMID 40486871, 2025).
Alzheimer disease (3 papers, 2023). A progressive, neurodegenerative disease characterized by loss of function and death of nerve cells in several areas of the brain leading to loss of cognitive function such as memory and language. "Seven of these genes are Alzheimer’s disease-related, six are down-regulated with both Apoer2-ICDs (COX7A2L, FZD2, KIF5A, MAP2K2, PSENEN, RAF1) and one with only the Apoer2-ICD[Δ19] (SLC39A9)." (PMID 37461529, 2023).
breast tumor (1 paper, 2016). "Statistical analysis of Zn transporter expression indicated that similar to what was observed in breast tumor tissues, basal-like cancer cells also had significantly higher expression of MTs and SLC39A14 and lower expression of SLC39A6, SLC39A9, and SLC39A11 (fold-change >1.5; FDR, p < 0.05)." (PMID 26728511, 2016).
viral infection (1 paper, 2024). "Subsequent infection of Huh7.5.1-VP30 cells with cleaved or uncleaved viruses, followed by assessment after two days using flow cytometry, demonstrating that SLC39A9 deficiency significantly reduced EBOVΔVP30-EGFP virus infection, consistent with our results." (PMID 39173055, 2024). "Secondly, the functional roles attributed to PIK3C3 and SLC39A9 in EBOV infection are primarily based on viral infection assays conducted in vitro using genetic knockout cells, where the efficiency of knockout varied." (PMID 39173055, 2024). "Importantly, the genetic complementation of PIK3C3 and SLC39A9 KO cells with their respective cDNAs restored EBOVΔVP30-EGFP viral infection to a level comparable to that of sgNC-transduced cells, excluding the off-target effect of the sgRNA." (PMID 39173055, 2024). "Moreover, genetic depletion of PIK3C3 or SLC39A9 not only decreased virus infection but also significantly diminished EBOV RNA levels in infected cells and progeny virus production." (PMID 39173055, 2024). "Notably, the most significant decreases in viral infection were observed with the loss of PIK3C3 and SLC39A9, resulting in a 70% and 50% reduction in viral infection respectively." (PMID 39173055, 2024). "While changes in cellular zinc levels slightly affected EBOV infection in both WT and SLC39A9 KO cells, neither the increase nor decrease in cellular zinc levels could rescue the decreased viral infection caused by SLC39A9 depletion." (PMID 39173055, 2024). "This suggests that recombinant SLC39A9 may compete with plasma membrane-localized SLC39A9 for interaction with EBOV, thereby blocking viral infection." (PMID 39173055, 2024). "Moreover, SLC39A9-Flag specifically co-precipitated with NPC1-HA and viral GP proteins upon EBOVΔVP30-EGFP infection (lane 8 vs. lane 7), further confirming their interaction in the context of virus infection." (PMID 39173055, 2024). "Our data showed that SLC39A9, NPC1 and viral GP could co-localized upon viral infection." (PMID 39173055, 2024). "To strengthen this point in the context of viral infection, we infected the Huh7-NPC1-EGFP/SLC39A9-Flag cells with EBOVΔVP30-EGFP or not." (PMID 39173055, 2024).
cancer (18 papers, 2015 to 2025). A tumor composed of atypical neoplastic, often pleomorphic cells that invade other tissues. "Recent research has unveiled that knockout of the Zn2+-transporter SLC39A9 (ZIP9), alongside the well-described targets C1GALT1 (C1GalT1) and its molecular chaperone, C1GALT1C1 (COSMC), results in surface-expression of cancer-associated O-glycans." (PMID 38699634, 2024). "While KIT mutations are well-known drivers of GIST, tissue-specific genes such as the serine/threonine protein kinase TESK1, the myelin regulatory factor MYRF, as well as the 5-oxo-L-prolinase OPLAH or the zinc influx transporter SLC39A9 have not been associated with cancer before." (PMID 26102504, 2015). "Of the differentially expressed genes, IFI6, SLC39A9 and ZNF185 showed a strong correlation with tumor progression and patient survival in the OncoLnc database while roles for AKAP12 and DUSP5 in carcinogenesis and poor prognosis have previously been established for other cancer types." (PMID 32849815, 2020).
infection (2 papers, 2023 to 2024). The state of being infected such as from the introduction of a foreign agent such as serum, vaccine, antigenic substance or organism. "Furthermore, our findings revealed that recombinant SLC39A9 could inhibit EBOVΔVP30-EGFP infection in a dose-dependent manner, whereas an unrelated Varicella-Zoster Virus (VZV) glycoprotein E (VZV gE) showed no such effect." (PMID 39173055, 2024). "Notably, unlike the phenotype caused by SLC39A9 knockout, we found that C1GalT1 knockout in Huh7.5.1-VP30 cells did not impair EBOVΔVP30-EGFP infection, indicating that SLC39A9-mediated glycosylation has limited effect on EBOV infection." (PMID 39173055, 2024).
SLC39A9 also shares sentences with these, for which no sentence is quoted: breast carcinoma (14 papers); prostate carcinoma (14); Zinc deficiency (7); tumor (6); melanoma (3); hepatocellular carcinoma (2); male infertility (2); cervical cancer (1); endometrial cancer (1); gastric adenocarcinoma (1); glioblastoma (1); glioma (1); ischemia (1); liver cancer (1); memory impairment (1); metastatic melanoma (1); myocardial ischemia (1); neuroblastoma (1); nevus (1); Obesity (1); ovarian carcinoma (1).